MUC1 (mucin 1, cell surface associated)
Diseases named in the same sentence as MUC1 in open-access papers (continued):
Sharing a sentence is not in itself a finding about the gene and the disease.
ovarian carcinoma (continued). "The presence of TAG72 has been confirmed on MUC1 and CD44 (an ovarian cancer stem cell marker and receptor for the ECM molecule hylauronan) as well as CD133 (a marker present in cancer stem-cells including ovarian cancer) and MUC16 proteins in ovarian cancer patients." (PMID 32937961, 2020). "Immunohistochemical detection of MUC1 via VU3C6 shows a correlation of MUC1 with pT but not with overall survival, grading, and FIGO in epithelial ovarian cancer patients." (PMID 34445181, 2021). "MUC1 and MUC4 levels have also been reported in mucinous ovarian carcinoma, but the implications of glycosylation on these mucins has not been explored in ovarian carcinoma." (PMID 32075174, 2020).
pulmonary fibrosis (127 papers, 2011 to 2025). Chronic progressive interstitial lung disorder characterized by the replacement of the lung tissue by connective tissue, leading to progressive dyspnea, respiratory failure, or right heart failure. "Genes prioritised by functional evidence at these signals included MUC1, which encodes a large transmembrane glycoprotein and known biomarker of lung fibrosis, and NTN4 encoding Netrin-4 whose known roles include angiogenesis." (PMID 39974050, 2025). "Bleomycin-induced lung fibrosis was decreased in MUC1-deficient mice, and in vitro silencing of MUC1 expression diminished fibroblast proliferation." (PMID 35479093, 2022). "Similarly, MUC1 is prominently expressed in lung epithelial cells and its glycoprotein subtype KL-6 has been established as a diagnostic marker for pulmonary fibrosis." (PMID 40750896, 2025). "Increased MUC1 is found in both bronchoalveolar lavage and serum from those with pulmonary fibrosis, while it is present in less than 10% of serum samples from patients with chronic lung diseases." (PMID 40943651, 2025). "In the context of IPF, overexpression of MUC1 has been observed in lung tissue from pulmonary fibrosis patients." (PMID 31514468, 2019). "MUC5B had a similar expression profile to MUC1, being most elevated in the sigmoid colon, but is a secreted polymeric mucin that can be dysregulated in the lung of subjects with idiopathic pulmonary fibrosis." (PMID 22829946, 2012). "Both SP-D and KL-6/MUC1 are established biomarkers of the interstitial pneumonias, including idiopathic pulmonary fibrosis (IPF), but the causes and clinical outcomes based on their independent effects are not known." (PMID 21637370, 2011). "However, KL-6 has been reported to be detectable in mice expressing human MUC1(hMUC1-exp) mice and can reflect the severity of bleomycin-induced lung fibrosis." (PMID 37409133, 2023). "We have also observed IPF overexpression of the transmembrane mucins, Muc1, Muc4, and Muc16 (unpublished data), which may be involved in the molecular processes that lead to the development of pulmonary fibrosis." (PMID 30704051, 2019). "Other examples of feasible IPF and LC-IPF treatment candidates include vantictumab, which interferes with Wnt signalling and has undergone Phase I trials for NSCLC (preclinical studies of Wnt pathway inhibition have also been performed in pulmonary fibrosis), and Muc1-based therapeutic strategies." (PMID 30704051, 2019). "Consequently, we assessed the role of MUC1 rs4072037 and serum KL-6 levels as a potential biomarker of ASSD susceptibility and for the differential diagnosis between patients with ILD associated with ASSD (ASSD-ILD +) and idiopathic pulmonary fibrosis (IPF)." (PMID 34799647, 2021). "Furthermore, preclinical studies have demonstrated that antibodies against KL-6 attenuate bleomycin-induced lung fibrosis, while MUC1 knockout (KO) mice exhibit resistance to bleomycin-induced pulmonary fibrosis, with improvements in lung function, survival and fibrotic lung tissue remodelling." (PMID 31514468, 2019). "For example, a recent study showed that the presence of the MUC1 rs4072037 C allele increases the risk of antisynthetase syndrome (ASS) and it could be a useful genetic biomarker for the differential diagnosis between ASS-ILD + and idiopathic pulmonary fibrosis patients." (PMID 38743787, 2024). "Upregulation of MUC1-ED sheddases in these cells during disease manifestation remains an alternative possibility, and elevated levels of MMP-14 have been described in pulmonary fibrosis." (PMID 35479093, 2022). "Mice with BLM-induced lung fibrosis treated with anticorisin mAtb showed low plasma and BALF levels of osteopontin and MUC-1, reduced BALF MUC5B level, decreased number of apoptotic lung cells, and reduced cleavage of caspase-3." (PMID 35322016, 2022).
pulmonary fibrosis (continued). "In an experimental model of silica-induced pulmonary fibrosis using mice expressing the human MUC1 transgene, BALF and serum levels of MUC1 were increased compared with saline controls." (PMID 35479093, 2022). "KL‐6/MUC1 is one of the key molecules involved in the intra‐alveolar fibrotic process and pulmonary fibrosis." (PMID 34646945, 2021). "We observed elevated levels of sftp-D, muc-1, eotaxin, muc-1, chymase, tryptase, and plasmonigen activator inhibitor-I (PAI-1: a key factor for lung fibrosis) in the lungs of infected hamsters." (PMID 34721035, 2021). "Mice with BLM-induced lung fibrosis receiving intratracheal corisin showed a significantly increased BALF total number of lymphocytes and enhanced BALF levels of MUC-1, periostin, osteopontin, and collagen I compared to counterpart mice receiving intratracheal scrambled peptide." (PMID 35322016, 2022).
interstitial lung disease (126 papers, 2008 to 2026). A diverse group of lung diseases that affect the lung parenchyma. "The serum level of KL-6/MUC1 reflects the severity of interstitial lung disease associated with connective tissue disease." (PMID 34572367, 2021). "The sialylated carbohydrate antigen KL-6, identified as human MUC1, serves as a biomarker for interstitial lung disease." (PMID 39469649, 2024). "Serum KL-6 is a mucinous high-molecular-weight glycoprotein classified as human MUC1 mucin, which has been reported to serve as a sensitive marker for interstitial lung diseases." (PMID 36983404, 2023). "Indicative of a functional role for increased MUC1 expression in respiratory disorders, the sialylated carbohydrate antigen Krebs von den Lungen 6 [KL-6, now identified as human MUC1], is a marker for interstitial lung disease." (PMID 31069176, 2019). "KL-6, a human MUC1 mucin, is a sensitive biomarker for interstitial lung diseases including pulmonary alveolar proteinosis (PAP)." (PMID 27108412, 2016). "It is a substance produced by Type II alveolar epithelial cells in the lungs, is now classified as a human MUC1 mucin protein, and regenerating Type II pneumocytes are the primary cellular source of KL-6/MUC1 in the affected lungs of patients with interstitial lung diseases (ILDs)." (PMID 39372036, 2024). "KL-6/MUC-1 (KL-6) and surfactant protein D (SP-D) are useful biomarkers in the diagnosis of various types of interstitial lung disease (ILD), including IPF." (PMID 22530118, 2012). "Alveolar epithelial markers, such as surfactant protein-D (SP-D), Krebs von den Lungen-6 (KL-6), and mucin 1 (MUC-1), have been used as part of clinical practice for the diagnosis of interstitial lung diseases (ILDs) in Japan for more than a decade." (PMID 39597967, 2024). "KL-6 is classified as a human MUC1 mucin protein and is one of the key molecules in interstitial lung diseases." (PMID 35953795, 2022). "KL-6, a human MUC1 mucin protein, is a potential biomarker for diagnosing and predicting the severity and mortality of interstitial lung disease." (PMID 35204430, 2022). "Serum Krebs von den Lungen-6 (KL-6), which is classified as human mucin-1 (MUC1), is used as a marker of sarcoidosis and other interstitial lung diseases." (PMID 22650152, 2012).
gastric cancer (112 papers, 2003 to 2026). A primary or metastatic malignant neoplasm involving the stomach. "It was demonstrated by studies in a Portuguese population that the smaller MUC1 VNTR alleles are associated with an increased risk of gastric carcinoma as well as of chronic atrophic gastritis." (PMID 41154387, 2025). "We evaluated the association between polymorphism rs4072037G>A MUC1 gene with Helicobacter pylori in patients with gastric cancer in a case-control study." (PMID 38463926, 2024). "Relationship between rs4072037G>A polymorphism of MUC1 gene and increased susceptibility to H. pylori infection aimed to investigate in patients with gastric cancer in Mazandaran, northern Iran." (PMID 38463926, 2024). "The MUC1 gene encodes glycoproteins attached to cell membrane that play a protective role in gastric cancer and protect epithelial surfaces against external factors such as Helicobacter pylori." (PMID 38463926, 2024). "Functional polymorphism rs4072037 in MUC1 gene involved in inflammatory response in patients with H. pylori is significantly associated with a predisposition to gastric cancer." (PMID 38463926, 2024). "Association between rs4072037 G>A polymorphism of MUC1 gene and susceptibility to H. pylori in patients with gastric cancer (H." (PMID 38463926, 2024). "Previous studies have shown that MUC1 gene polymorphisms are associated with susceptibility to gastric cancer." (PMID 38463926, 2024). "Likely, studies have reported significant associations between the positive expression of MUC1 and clinicopathological features with poor prognosis of gastric cancer, including the advanced clinical stage and positive lymph node metastasis." (PMID 36831343, 2023). "In a meta-analysis, MUC1 expression was associated with the intestinal-type of gastric cancer (OR 1.76; 95% CI 1.27–2.44)." (PMID 36831343, 2023). "Our study results showed that MUC1 expression was significantly associated with pathological features of poor prognosis in gastric cancer." (PMID 36831343, 2023). "The A allele associates with gastric cancer by lowering MUC1 expression on the surface of epithelial cells lining the gastric mucosa." (PMID 34532288, 2021). "The result on the association between gastric cancer risk and a combination of MUC1 polymorphisms (rs4072037 and rs2070803) and male gender once again showed that rs4072037 AA and rs2070803 GG were the two genotypic risk factor for stomach cancer." (PMID 34532288, 2021). "Two SNPs rs4072037 and rs2070803 of MUC1 gene were found to be genotypic risk factors of gastric cancer." (PMID 34532288, 2021). "In particular, in a recent meta-analysis with 10,092 gastric cancer cases and 15,236 controls, Peixi Liu clearly showed MUC1 rs4072037 polymorphism was protective against the onset of gastric cancer." (PMID 34532288, 2021). "In summary, this is the first large multicenter case–control study in Vietnamese population to investigate the effect of two SNPs rs4072037 and rs2070803 in MUC1 gene as the risk factor for gastric cancer." (PMID 34532288, 2021). "Several genome-wide association studies (GWASs) have revealed a significant association of MUC1 polymorphisms with the risk of gastric cancer." (PMID 34638981, 2021). "They suggested MUC1 (rs4072037) polymorphism slightly decreased risk of gastric cancer among Asian population, and this was associated with decreased risk with different genotypes except for homozygous recessive (AA) in Caucasian population." (PMID 32660489, 2020). "Data from this study revealed that the MUC1 rs4072037 polymorphism was significantly associated with decreased risk of gastric cancer." (PMID 32660489, 2020). "The G allele at rs4072037 of MUC1 gene was associated with a significant decreased gastric cancer risk (OR = 0.507, 95% CI: 0.322–0.799, p = 0.003)." (PMID 32660489, 2020). "Hypoglycosylated or tumor-associated MUC1 (TA-MUC1) expression in tumor cells was present in 90.6% of AN gastric cancer patients." (PMID 31941061, 2020).
gastric cancer (continued). "Recently, studies of the genome-wide association in Japanese and Chinese populations identified chromosome 1q22 harboring the gene MUC1 as a locus that confers susceptibility to the development of gastric cancer." (PMID 28512631, 2017). "Published data on the association between the MUC1 rs4072037A > G polymorphism and gastric cancer (GCa) risk were inconclusive." (PMID 26910281, 2016). "In contrast, MUC1 rs4072037 T>C polymorphism was shown to significantly decreased stomach cancer susceptibility under the homozygous model (CT vs. TT: adjusted OR = 0.77, 95% CI = 0.60–0.98)." (PMID 25658482, 2015). "In the current hospital based case-control study, we investigated the potential associations of PSCA rs2294008 C>T and rs2976392 G>A, PLCE1 rs2274223 A>G and MUC1 rs4072037 T>C polymorphisms with stomach cancer susceptibility among a Chinese population." (PMID 25658482, 2015). "It was found that the MUC1 rs4072037 G allele was significantly associated with a decreased gastric cancer risk (OR = 0.72, 95% CI = 0.68–0.77), when compared with the A allele." (PMID 25658482, 2015). "As to the MUC1 rs4072037 T>C polymorphism, the association between this polymorphism and gastric cancer was validated among different ethnicities." (PMID 25658482, 2015). "Since MUC1 polymorphism has been reported to be associated with gastric cancer, several studies were performed to validate this finding." (PMID 25332893, 2014). "The association between MUC1 polymorphism rs4072037 and the risk of gastric cancer has been described in several studies." (PMID 25332893, 2014). "In conclusion, our meta-analysis summarizes the existing data on MUC1 polymorphism rs4072037 and gastric cancer susceptibility." (PMID 25332893, 2014). "Overall, the G allele at rs4072037 of MUC1 gene was associated with a significant decreased gastric cancer risk (OR=0.70, 95% CI: 0.64–0.76)." (PMID 25332893, 2014). "In summary, this meta-analysis suggested that the MUC1 rs4072037 polymorphism was significantly associated with decreased risk of cancer, especially for gastric cancer and Asian population." (PMID 24755768, 2014). "Genome-wide association studies have identified a susceptibility variation MUC1 rs4072037 for gastric cancer in Chinese population." (PMID 24755768, 2014). "Odds ratios with 95% confidence intervals were calculated to assess the strength of the association between MUC1 rs4072037 and risk of gastric cancer." (PMID 25332893, 2014). "The association between MUC1 polymorphism rs4072037 and the risk of gastric cancer has been described in previous studies with a candidate gene approach." (PMID 25332893, 2014). "An association between elevated levels of MUC1 IgG abs and a benefit in survival was observed in patients with lung, pancreatic, breast and gastric cancer." (PMID 24212946, 2011). "MUC1 IgG responses have been associated with a benefit in survival in patients with breast, lung, pancreatic, ovarian and gastric carcinomas." (PMID 24212946, 2011). "Several studies have linked MUC1 polymorphisms with susceptibility to H. pylori-induced disease, such as gastritis and gastric cancer, suggesting a direct effect of MUC1 polymorphisms on the development of Helicobacter-associated pathology." (PMID 19816567, 2009). "Susceptibility to Helicobacter pylori gastritis and to gastric cancer appears to be associated with MUC1 allele length." (PMID 19238635, 2008). "We report that MUC1 is upregulated in EBV-associated gastric cancers (EBVaGCs)." (PMID 40764753, 2025). "This variant is first and foremost known for its association with gastric cancer, and in this context, it is believed rs4072037 influences the quantity and/or the quality of the MUC1 protein." (PMID 37877466, 2023).
gastric cancer (continued). "The MUC1 expression in gastric cancer tissues was significantly associated with aggressive pathological features including diffuse histologic type, deeper layer of tumor invasion, perineural invasion, lymphovascular invasion, lymph node, and distant metastasis." (PMID 36831343, 2023). "Furthermore, subgroup analysis in early gastric cancer patients showed a significant association between the high level of MUC1 expression and lymphovascular invasion." (PMID 36831343, 2023). "In genome-wide association studies (GWASs), differences in frequency of the single nucleotide polymorphism (SNP) frequencies on the MUC1 gene were shown according to the Lauren classification of gastric cancer (intestinal type vs. diffuse type) and ethnic groups." (PMID 36831343, 2023). "The low expression of MUC1 may increase the susceptibility to gastric cancer due to the reduced protective function of stomach." (PMID 34532288, 2021). "Therefore, MUC1 rs4072037 polymorphism was associated with decreased risk of gastric cancer in northern Iran." (PMID 32660489, 2020). "One of the most well-known is the association of MUC1 with gastric cancer." (PMID 32701958, 2020). "However, MUC1 expression in gastric cancer was associated with biologically aggressive phenotypes such as vascular invasion (OR = 1.64, 95% CI: 1.13–2.39, P = 0.009 fixed-effect) and lymph node metastasis (OR = 2.10, 95% CI: 1.20–3.67, P = 0.01 random-effect)." (PMID 27190429, 2016). "Compared with the low-risk allele, the high-risk allele of SNP rs4072037 in MUC1, with a frequency of 89% in the group of all gastric cancer cases under 50 years of age, had a per-allele risk of 1.76 (95% CI 1.01-3.05, P = 0.045*) adjusted for sex and age in an unconditional logistical model." (PMID 27127881, 2016). "We found that PSCA rs2294008 CT/TT, PSCA rs2976392 AG/AA and PLCE1 rs2274223 AG/GG genotypes were associated with a significantly increased stomach cancer risk in a Chinese population, whereas, the MUC1 rs4072037 T>C were associated with decreased stomach cancer susceptibility." (PMID 25658482, 2015). "Therefore, we performed this meta-analysis to evaluate the relationship between MUC1 gene polymorphism at rs4072037 and gastric cancer susceptibility and assess the effect size of the association in order to clarify the inconsistency among published studies." (PMID 25332893, 2014). "Therefore, we performed the first meta-analysis to assess the relationship between MUC1 gene polymorphism rs4072037 and gastric cancer susceptibility." (PMID 25332893, 2014). "In addition, subgroup analyses revealed that MUC1 rs4072037 G allele was associated with a decreased risk for progress of gastric cancer,especially in Asians." (PMID 24755768, 2014). "Further, subgroup analysis based on ethnicity suggested MUC1 rs4072037 polymorphism had a subtly reduced cancer risk among Asian population, and stratified analysis by cancer types showed significantly decreased risk of gastric cancer in all genetic models." (PMID 24755768, 2014). "In conclusion, MUC1 rs4072037 polymorphism may be used as potential biomarker for cancer susceptibility particularly for gastric cancer and for Asian population." (PMID 24755768, 2014). "Our findings demonstrate that the presence of the G allele at rs4072037 of the MUC1 gene may contribute to protection against gastric cancer in Asian." (PMID 25332893, 2014). "Therefore, we performed this meta-analysis to evaluate the relationship between MUC1 gene polymorphism and gastric cancer susceptibility." (PMID 25332893, 2014). "Moreover, aberrant glycosylation and loss of apical expression of MUC1 have been reported for gastric carcinomas." (PMID 22073229, 2011). "VNTR analysis of MUC1 found an association between short alleles and gastric cancer." (PMID 18000536, 2007). "Subsequently, studies found that MUC1 can promote GC metastasis, is associated with poor prognosis, and appears to be involved in the progression of diffuse gastric cancer (DGC)." (PMID 37894512, 2023).